ENSG00000269242 (novel transcript)
Gene: Protein-coding gene on chromosome 19 (12,643,831 to 12,648,397, reverse strand). Ensembl gene ENSG00000269242.
Genetic constraint (gnomAD): Missense variants: 280 observed, 273 expected, observed/expected ratio (o/e) 1.03, 90% interval 0.93 to 1.13. Synonymous variants: 128 observed, 127 expected, observed/expected ratio (o/e) 1.01, 90% interval 0.87 to 1.17.